IRF3 (interferon regulatory factor 3)
Diseases named in the same sentence as IRF3 in open-access papers (continued):
Sharing a sentence is not in itself a finding about the gene and the disease.
melanoma (continued). "To investigate whether the effects of STING-TBK1-Zyxin signaling were relied on IRF3, we inoculated B16-F10 melanoma cells into WT, Sting1−/−, Irf3−/−, or Zyxin−/−;Irf3−/− mice." (PMID 39304793, 2024). "The activation of the STING pathway by VPS34 inhibition was not limited to the RCC cells but similarly observed in the Me30966 melanoma cell line as evidenced by increased IRF3 and STAT1 phosphorylation (lanes 3 and 5) in a STING‐dependent manner (lanes 4 and 6)." (PMID 38506049, 2024). "Indeed, we demonstrated that upon doxorubicin treatment TG2 translocates into the nucleus of apoptotic melanoma cells interacting with IRF3 dimers." (PMID 36572679, 2022). "In addition, we confirmed the presence of IRF3 covalent dimers upon doxorubicin treatment also in Hela cells, thus suggesting that the TG2 posttranslational modification of IRF3 is not limited to melanoma cells." (PMID 36572679, 2022). "Besides its key role in antiviral immunity, IRF-3-mediated apoptosis in response to dsRNA was observed in melanoma and fibrosarcoma cells." (PMID 25444175, 2015). "As the IFN-regulatory role of IRF3 plays a pivotal part in this, we tested whether the non-coding mutations we had identified could affect immunotherapy response in individuals with melanoma." (PMID 40359938, 2025). "Interestingly, these noncoding mutations also tend to associate with a worse response to immunotherapy in melanoma patients, which may relate to the function of IRF3 (interferon regulatory factor 3) in innate immunity." (PMID 41278537, 2025). "Whole-exome sequencing of human melanoma tissues and the human melanoma cell line revealed that acquired resistance can result from loss-of-function mutations of IFNGR1, IFNGR2, JAK1, JAK2, STAT1, and IRF3 from the IFN-γ signaling pathway and β2M from antigen presentation pathway." (PMID 35432377, 2022). "Taken together, these data demonstrate that TG2 negatively regulates the IRF3 pathway in human melanoma cells suggesting a so far unknown TG2-dependent mechanism by which cancer cells reduce the IFNI production after DNA damage to limit the immune system response." (PMID 36572679, 2022). "Increased levels of phosphorylated STING and IRF3 were observed after treatment with Mn-ZIF-8 in combination with IR (6Gy), indicating that Mn‐ZIF‐8 contributed to activation of the STING pathway in melanoma cells induced by RT." (PMID 40585994, 2025). "Illumina-based RNA-seq as well as direct cDNA long-read nanopore sequencing confirmed that Mel-ST cells express the same IRF3 and BCL2L12 isoforms as we had observed in melanoma tumors." (PMID 40359938, 2025). "Taken together, these results indicate that TG2 protein expression, as well as its nuclear translocation, IRF3 covalent dimers, and IFNI production occur exclusively in dying melanoma cells." (PMID 36572679, 2022). "A strong correlation between expression of RIG-I (DDX58) pathway genes (DDX58, IRF1, IRF3) and HLA-I APM genes, was also detected in melanoma biopsies from ICB-treated patients." (PMID 33554047, 2021). "This bidirectional regulatory pattern was particularly evident in STAT1 and IRF3 downstream signatures, further supporting the hypothesis that CCRL2 serves as a key modulator of innate immune gene programs in melanoma cells." (PMID 40867595, 2025). "SPOP loss consistently increased STING protein levels, but not those of cGAS, TBK1, or IRF3, across human melanoma (A2058, HMCB, and MeWo), mouse melanoma (B16), human RCC (A498, 786-o, and UMRC6), mouse RCC (Renca), and HEK293 cells." (PMID 41148213, 2025). "In addition, the expression and activation of IRF3 and IRF7 proteins was enhanced in melanoma cells with NGLY1 knockdown." (PMID 30385822, 2018).
melanoma (continued). "Although ectopic expression of IRF-3 was previously shown to suppress the growth of HeLa cervical cancer cells and B16 melanoma tumors, thus far, the involvement of IRF-3 expression in human cancer tissues has not been studied extensively." (PMID 23658645, 2013). "By measuring the level of STING, TBK1 and IRF3 phosphorylation in pDCs exposed to melanoma supernatants, we could not detect evidence of molecular impairment of the STING pathway." (PMID 38239354, 2023).
ZIKV infection (31 papers, 2017 to 2025). "We also assessed the impact of HOIP loss on IRF3 and NF-κB P65 nuclear translocation during ZIKV infection." (PMID 38001254, 2024). "Following intravenous inoculation, Irf3−/−Irf5−/−Irf7−/− TKO were more susceptible to ZIKV infection than Ifnar1−/− mice indicating a potential role for IRF-3-dependent, IFN-α/β-independent restriction mechanisms." (PMID 28608813, 2017). "In this study, TRIM38 overexpression in U251 cells increased the expression of RIG-I/MDA5 signaling pathway-related proteins, including RIG-I, MDA5, TBK1, and IRF3, at 6 h post-ZIKV infection, and also increased the IFN-β level." (PMID 40006954, 2025). "OASL-IT1, a type of ncRNAs, can trigger production of IFN-β by regulating IRF3 and NF-κB positively to help epithelial cells resist ZIKV infection." (PMID 37416780, 2023). "Because of the ZIKV infection interferon receptor (Ifnar1-/-) or Irf3-/-Irf5-/-Irf7-/-, triple-knockout mice developed neurological disease and sustained high viral loads in the brain, spinal cord, and testes." (PMID 36831177, 2023). "Recently, it has been shown that NS5 interacts with IRF3 localized in the nucleus to inhibit the transcription of type I IFNs during ZIKV infection." (PMID 37416780, 2023). "To determine if TTP induction is mediated by IRF3 activation following ZIKV infection, we transduced hBMECs to express a dominant negative IRF3 (IRF3Δ60) that lacks the ability to induce IFNβ." (PMID 37707056, 2023). "The main transcription factors in innate immunity to ZIKV infection include NF-κB, IRF-3, and IRF-7." (PMID 36831177, 2023). "Mice with triple knockout of Irf3, Ifr5, and Irf7 were highly vulnerable to subcutaneous, intraperitoneal, or intravenous ZIKV infection and developed neurological diseases such as hindlimb weakness and paralysis." (PMID 36146595, 2022). "Recent studies confirmed that ZIKV infection suppresses type I IFN induction by downregulating IRF3- and NK-κB-mediated signaling." (PMID 36014974, 2022). "In immunodeficient Ifnar1−/− and Irf3−/−Irf7−/− mice, vaginal ZIKV infection induced higher levels of viral replication." (PMID 36146595, 2022). "In contrast, Zika virus infection stimulates the RIG-I/MAVS/IRF3 pathway and downstream IFN-β expression, which increases HLA expression in infected cells." (PMID 32321802, 2020). "Quantitative RT-PCR analyses revealed that ZIKV infection-triggered ISGs expression was almost completely abrogated in p65 or IRF3 KO organoids." (PMID 30952992, 2019). "AG129 and Irf3/5/7 TKO mice are the immunocompromised mice which were permissive to different strain ZIKV infection and vulnerable to ZIKV-relative pathology and lethality." (PMID 30356305, 2018). "Previous work has demonstrated that wild-type immunocompetent mice are resistant to ZIKV pathogenesis but that mice lacking alpha/beta interferon (IFN-α/β) signaling (e.g., Ifnar1−/−, A129, AG129, Irf3−/− × Irf5−/− × Irf7−/−) succumb to ZIKV infection." (PMID 28270583, 2017). "The findings described herein characterize the IRF3/7 DKO mouse model for use in ZIKV infection studies." (PMID 28420392, 2017). "Interestingly, in the human H9 cell line, ZIKV infection leads to an upregulation of p65 and IRF3 in response to viral infection." (PMID 38137537, 2023). "We found that although ZIKV infection induced phosphorylation of IRF3 in SC, this was dramatically diminished by R428 treatment, suggesting that IFNB1 and IFNL1 transcription in SC is responsive to ZIKV genome replication and not directly modulated by Axl-IFNAR signaling." (PMID 31311882, 2019). "An open question in our current study is whether IRF3 and NF-κB have equal or differential effects upon ZIKV infection." (PMID 30952992, 2019). "Future studies are apparently needed to investigate whether there is a difference of virus entry, virus replication or cell survival between IRF3 and NFκB KO cells upon ZIKV infection." (PMID 30952992, 2019).
ZIKV infection (continued). "In all ISGs tested, administration of IFNAR blocking antibody could not ameliorated ZIKV-induced ISGs activation, supporting an IFN-independent ISG induction via activation of IRF3 and NF-κB upon ZIKV infection in NPCs." (PMID 30952992, 2019). "A recent study on human Sertoli cells showed that Zika virus infection can counteract BMP6 signaling, and that BMP6 induces phosphorylation of IRF3 and STAT1, and increases expression of IFNβ and some ISGs." (PMID 38308064, 2024). "The IRF3 and RIG-I axis plays an important role during ZIKV infection, as one of the main sensors for this virus." (PMID 36851534, 2023). "We evaluated the crosstalk between RIG-I and DNA-PKcs during ZIKV infection analyzing the IFN-I/III-inducing transcription factors including IRF1, IRF3, IRF5, IRF7, and p65 (NF-κB subunit)." (PMID 36311766, 2022). "Surprisingly, we observed IRF3 and STAT2 degradation in macrophages at early times of ZIKV infection." (PMID 31673117, 2019). "It was of interest that the degradation of IRF3 and STAT2 in macrophages took place at early hours of ZIKV infection, clearly before viral protein expression occurred." (PMID 31673117, 2019). "Since both the Asian and African lineage Zika viruses induced cytokine gene expression in human DCs and also weakly in macrophages, we analyzed the level of phosphorylation of IRF3 and STAT2 in response to ZIKV infection." (PMID 31673117, 2019). "In response to ZIKV infection, IFNβ was induced in WT hBMECs but not IRF3Δ60-hBMECs, and IRF3Δ60 expression dramatically reduced IRF3-directed ISG expression." (PMID 37707056, 2023). "Numerous studies have shown that ZIKV interacts with sensory molecules, such as toll-like receptor 3 (TLR3) and retinoic acid inducible gene 1 (RIG-1), as well as the transcription factors interferon regulatory factor 3 (IRF7) and NFκ-B, following ZIKV infection." (PMID 36014974, 2022). "Consistently, it has been reported that ZIKV infection of hNPCs activates, depending on the presence of IRF3 and NF-κB, ISGs but not IFN." (PMID 33658344, 2021). "This analysis revealed IRF3 phosphorylation upon ZIKV infection in wt and MDA5 KO cells, but not in RIG-I KO cells." (PMID 32560274, 2020). "Ablation of p65 or IRF3 in hESCs did not interfere regular neural differentiation programs and ZIKV infection." (PMID 30952992, 2019). "An early degradation of IRF3 and other molecules regulating pathogen recognition could lead to impaired IFN responses during ZIKV infection." (PMID 31673117, 2019). "However, knockout mice for INFAR 1, IRF3, IRF5, and IRF7 remained susceptible to ZIKV infection and developed neurological disorders but did not succumb to the infection." (PMID 38137537, 2023). "MAVS and IRF3 mice did not experience weight loss, morbidity, or mortality, suggesting that MAVS and IRF3 might not be required for the antiviral response to ZIKV infection in mice." (PMID 38137537, 2023). "In cells stably expressing TLR3, activation of IRF3 was not substantially affected; however, we observed an ∼50% reduction of STAT1 phosphorylation during ZIKV infection." (PMID 33658344, 2021). "Furthermore, we showed ZIKV infection fails to induce IRF1 and IRF3 accumulation to the nucleus in absence of the RNA sensor RIG-I, suggesting DNA-PKcs is not a ZIKV sensor receptor." (PMID 36311766, 2022). "We observed that ZIKV infection induces IRF1 and IRF3, but not IRF5 and IRF7 nuclear accumulation." (PMID 36311766, 2022). "ZIKV infection directly activated a subset of IFN-stimulated genes (ISGs) in human NPCs, which depended on the presence of IRF3 and NF-κB rather than IFN production and secretion, highlighting a key role of IFN-independent acute antiviral pathway underlying ZIKV infection-caused neuropathy." (PMID 30952992, 2019).
Sepsis (30 papers, 2010 to 2026). Sepsis is defined as life-threatening organ dysfunction caused by a dysregulated host response to infection. "In particular, IRF3 signaling has been reported to be involved not only in sepsis but also in increased pathogen clearance associated with changes in the gut microbiota." (PMID 38375470, 2024). "This restoration of IRF3 expression aids in the clearance of pathogenic pathogens in response to sepsis." (PMID 39606629, 2024). "IRF3 (c.829G > A; p.Ala277Thr) variants were also encountered more commonly in the pediatric sepsis cohort than expected (adjusted p = 0.013)." (PMID 34973142, 2022). "While IRF3 clearly causes deleterious effects in sepsis and T. gondii infection, its role in liver diseases remains somewhat complex." (PMID 34619149, 2021). "In contrast, in pathogenic community infections, IRF3 restores the protective immunity in sepsis." (PMID 38375470, 2024). "However, the precise mechanisms underlying the regulatory role of FX-targeted IRF3 in modulating the composition of the bacterial flora and its subsequent impact on sepsis development remain unclear." (PMID 37762104, 2023). "The outcomes of IRF3 genetic expression indicated that LPS-exposed mice in the sepsis group showed markedly greater IRF3 gene expression than untreated controls." (PMID 41585603, 2026). "In our study, low, moderate, and high doses of L-carvone resulted in markedly lower IRF3 mRNA levels than observed in the sepsis group, thus confirming L-carvone's suppressive effects on late-stage NF-κB and type I IFN transcription." (PMID 41585603, 2026). "Meanwhile, the application of L-carvone in three doses resulted in significantly lower IRF3 levels than observed in the sepsis model." (PMID 41585603, 2026). "Fecal microbiota transplantation (FMT) rescued mice from lethal infection due to a pathogen community, isolated from a sepsis patient by restoring systemic immunity in an IRF3-dependent manner." (PMID 38375470, 2024). "Next, we focus on the role of IRF3 in sepsis, because IRF3 is not only an important molecule in the sepsis mortality but is also associated with important roles in microbiome." (PMID 38375470, 2024). "Here, we summarize the LPS recognition system, main findings related to the IRF3, and finally immunological gaps in sepsis." (PMID 38375470, 2024). "Fucoxanthin (FX), a carotenoid derived from brown algae, efficiently suppresses pro-inflammatory cytokine expression via IRF3 activation, thereby reducing mortality in a mouse model of sepsis." (PMID 37762104, 2023). "IRF3 promotes LPS-induced septic shock in mice; IRF3 knockout mice are resistant to LPS-mediated sepsis compared to Wt mice." (PMID 37515265, 2023). "FX had a strong inhibitory effect on acetic acid and propionic acid contents in the peritoneal lavage of mice with CLP sepsis, and these effects were mediated by IRF3." (PMID 37762104, 2023). "The infection of mice with human sepsis pathogens significantly reduced their number of butyrate-producing bacteria and inhibited the NF-κB and interferon regulatory factor 3 (IRF3) signaling pathways." (PMID 37111207, 2023). "In a CLP-induced sepsis mouse model, FX suppressed pro-inflammatory cytokine levels by inhibiting IRF3." (PMID 37762104, 2023). "FX significantly reduced the bacterial load in the abdominal cavity of mice with cecal ligation and puncture (CLP)-induced sepsis via IRF3 activation and increased short-chain fatty acids, like acetic and propionic acids, with respect to their intestines." (PMID 37762104, 2023). "This study aims to elucidate how FX-targeted IRF3 modulates intestinal microbiota compositions, influencing sepsis development." (PMID 37762104, 2023). "To examine the impact of FX on peritoneal and intestinal microbes in mice, we generated CLP sepsis models in wild-type (WT) and Irf3−/− mice." (PMID 37762104, 2023).
Sepsis (continued). "In mouse models, FMT has been seen to reverse the course of otherwise lethal human bacterial mediated sepsis by enhancing pathobiont clearance via the restoration of host immunity in an interferon regulatory factor 3-dependent manner." (PMID 34513724, 2021). "The less severe sepsis in cGAS-/- mice compared with WT mice supported previous reports of less severe CLP in mice with cGAS downstream signaling deficiency (STING and IRF-3)." (PMID 34768881, 2021). "TLR4 signaling pathway, including TLR4/NF-κB and TLR4/IRF3 pathways, contributes to the pathogenesis of sepsis, and the signaling is activated by LPS stimulation." (PMID 33869780, 2021). "Fecal microbiota transplant (FMT) reverses the course of otherwise lethal sepsis by enhancing pathogen clearance via the restoration of host immunity in an interferon regulatory factor 3-dependent manner." (PMID 32393794, 2020). "The Irf3−/− mice developed acute, symptomatic disease with sepsis and had dramatically increased bacterial numbers in bladders, kidneys and spleens (p<0.05), compared to wt mice, which were resistant to infection with E. coli 83972pap." (PMID 20886096, 2010). "Other key signaling pathways include sirtuin 6 (SIRT6), which promotes anti-inflammatory macrophage polarization and autophagy in septic lungs, and ankyrin demonstrated domain 22 (ANKRD22), which enhances M1 polarization via interferon regulatory factor 3 (IRF3) in sepsis-induced ARDS." (PMID 41488672, 2025). "Furthermore, in adoptive transfer experiments by using IRF3 KO bone marrow chimera, little protection from sepsis was shown, whereas chimeras with IRF3-KO stroma showed a substantial degree of protection." (PMID 38375470, 2024). "In sepsis models, such as CLP, IRF3 functions as an enhancer of sepsis." (PMID 38375470, 2024). "Previous studies have demonstrated that FX significantly reduces mortality in a CLP-induced sepsis mouse model via interferon regulatory factor 3 (IRF3), effectively suppresses pro-inflammatory cytokines and ROS, improves pathological damage, and activates autoimmune cells." (PMID 37762104, 2023). "Our current study suggested that TapSAKI silencing relieved LPS-induced injury in HK-2 cells at least in part by sponging miR-205 and regulating the IRF3 signaling pathway, highlighting a novel understanding for sepsis pathogenesis and a promising target for this disease treatment." (PMID 33869780, 2021). "For instance, we and others have demonstrated a role for IRF3 in the development of lethal sepsis." (PMID 34619149, 2021). "Finally, in both the gut-derived and IP models of sepsis herein described, IRF3 was observed to be downregulated with the progression of sepsis across organs, and treatment with FMT restored IRF3 to normal levels." (PMID 32393794, 2020). "Ppargc1a/b activation did not require NF-kβ, but did require an interferon response factor (IRF), because neither gene was activated in IRF-3/7 double-knockout mice in sepsis, but both were activated normally in Unc93b1-deficient (3d) mice." (PMID 21966468, 2011). "It is not known whether this may lead to a change in the clinical course of sepsis, but animal models showed an influence on sepsis mortality if IRF3 was pharmacologically inhibited." (PMID 20525286, 2010). "Moreover, in an animal model, IRF3 drove the pathogenesis of sepsis." (PMID 41212050, 2025). "The levels of STING, p‐TBK1, and p‐IRF3 in the hippocampus of mice in the CLP group were significantly greater than those in the Sham group indicating that the STING‐TBK‐IRF3 pathway in the hippocampus was activated during sepsis, which can further trigger neuroinflammation." (PMID 40016173, 2025). "However, IRF3 is also important and may be one of the therapeutic targets because it affects not only the sepsis induction but also the pathogen clearance via the restoration of host immunity." (PMID 38375470, 2024).